QPCT (glutaminyl-peptide cyclotransferase)
Description:
Responsible for the biosynthesis of pyroglutamyl peptides. Has a bias against acidic and tryptophan residues adjacent to the N-terminal glutaminyl residue and a lack of importance of chain length after the second residue. Also catalyzes N-terminal pyroglutamate formation. In vitro, catalyzes pyroglutamate formation of N-terminally truncated form of APP amyloid-beta peptides [Glu-3]-amyloid-beta. May be involved in the N-terminal pyroglutamate formation of several amyloid-related plaque-forming peptides.
Synonyms: QC; sQC; GCT
Tractability: Small molecule: a structure with a bound ligand is known; a high-quality ligand is known; it has a high-quality binding pocket; it belongs to a druggable protein family. Antibody: UniProt places it where antibodies can reach, with high confidence; its Gene Ontology location is reachable by antibodies, with high confidence; UniProt predicts a signal peptide or a membrane-spanning region. PROTAC: ubiquitination databases record sites on it; a small molecule that binds it is known.
Target class: Enzyme; Aminoacyltransferase
Gene: Protein-coding gene on chromosome 2 (37,342,827 to 37,373,322, forward strand). Ensembl gene ENSG00000115828.
Subcellular location: Secreted
Subcellular location (Human Protein Atlas): Cytosol; Predicted to be secreted
Pathways (Reactome):
Immune System: Neutrophil degranulation
Gene Ontology:
Molecular function: glutaminyl-peptide cyclotransferase activity; protein binding; zinc ion binding
Biological process: peptidyl-pyroglutamic acid biosynthetic process, using glutaminyl-peptide cyclotransferase; protein modification process
Cellular component: extracellular exosome; extracellular region; ficolin-1-rich granule lumen; specific granule lumen; tertiary granule lumen
Genetic constraint (gnomAD): Loss-of-function variants: 41 observed, 40.91 expected, observed/expected ratio (o/e) 1, 90% interval 0.78 to 1.3. The upper end of that interval is the gene's LOEUF score, 1.3, which puts it in group 5 of 6, group 1 being the genes least tolerant of losing a copy. Missense variants: 523 observed, 450.58 expected, observed/expected ratio (o/e) 1.16, 90% interval 1.08 to 1.25. Synonymous variants: 168 observed, 176.76 expected, observed/expected ratio (o/e) 0.95, 90% interval 0.84 to 1.08.
Homologues: Orthologues: chimpanzee QPCT (99% identical), macaque QPCT (94% identical), pig QPCT (88% identical), dog QPCT (86% identical), rat Qpct (83% identical), mouse Qpct (82% identical), rabbit QPCT (81% identical), guinea pig QPCT (80% identical), tropical clawed frog qpct (63% identical), zebrafish qpct (52% identical), Drosophila melanogaster isoQC (41% identical), Drosophila melanogaster QC (37% identical), and 3 more. Paralogues in human: QPCTL (48% identical).
Diseases named in the same sentence as QPCT in open-access papers:
QPCT is named in the same sentence as 33 diseases in open-access papers, as found by Europe PMC text mining. Sharing a sentence is not in itself a finding about the gene and the disease. The quoted sentences say what the papers report.
thyroid cancer (4 papers, 2019 to 2025). "Several previous studies have shown that glutamyl peptide transferase (QPCT), may be a biomarker for severe pancreatitis and that QPCT is strongly associated with the development of pancreatic and thyroid cancer." (PMID 39854580, 2025). "The analysis of microarray datasets identified QPCT as highly expressed in melanoma 54 and thyroid carcinomas 55-57." (PMID 31534544, 2019). "In contrast, genes such as TCDD-inducible poly (ADP-ribose) polymerase (TIPARP) and Glutaminyl-peptide cyclotransferase (QPCT), exhibited overexpression in thyroid carcinoma." (PMID 40346322, 2025).
melanoma (3 papers, 2006 to 2025). A malignant, usually aggressive tumor composed of atypical, neoplastic melanocytes. "QPCT has been reported to be overexpressed in melanoma and to complement the activity of QPCTL." (PMID 40717170, 2025). "Interestingly, the QPCT enzyme again was expressed at a level similar to well established antigens used in melanoma vaccines: MART1, MAGE3 and TYRP2." (PMID 16820060, 2006).
breast carcinoma (2 papers, 2015 to 2024). "Our present study found that QPCT overexpression promoted the proliferation, invasion, and migration of breast cancer cells, while QPCT knockdown inhibited cell proliferation, invasion, and migration." (PMID 38417050, 2024). "In this study, we found that glutaminyl-peptide cyclotransferase (QPCT) was a MTDH DOX resistance-related downstream gene in breast cancer." (PMID 38417050, 2024). "GEPIA database illustrated that QPCT was upregulated in most cancers, including breast cancer." (PMID 38417050, 2024). "Subsequently, the role of high expressions levels of QPCT and MTDH in promoting breast cancer progression and poor prognosis was validated both in breast cancer patients and through in vitro experiments." (PMID 38417050, 2024). "The most interesting genes for dairy breeds were breast cancer anti-estrogen resistance 3 (BARC3) and pituitary glutaminyl cyclase (QPCT), which are directly connected with the metabolism of the mammary gland." (PMID 25888030, 2015).
COVID-19 (2 papers, 2022 to 2024). A disease caused by infection with severe acute respiratory syndrome coronavirus 2. "Finally, six plasma proteins were found to mediate the causal effect between LTL and COVID-19 outcomes, such as BDNF, QPCT, FAS, MPO, SFTPB, and APOF." (PMID 38882679, 2024).
glioma (2 papers, 2022 to 2023). A benign or malignant brain and spinal cord tumor that arises from glial cells (astrocytes, oligodendrocytes, ependymal cells). "Glutaminyl-peptide cyclotransferase (QPCT), a macrophage-specific gene, was recently included in a model predicting worse outcomes in patients with gliomas." (PMID 37370678, 2023). "Interestingly, not much is known about the functions of OTUD1, TCHH, ADPRH, PLBD1, and QPCT in glioma, which need further research in future." (PMID 36389681, 2022).
Cirrhosis (1 paper, 2024). A chronic disorder of the liver in which liver tissue becomes scarred and is partially replaced by regenerative nodules and fibrotic tissue resulting in loss of liver function. "Therefore, we speculate that the upregulated expression of QPCT also enhances the modification of the N-terminus of CCl2 and leads to improved activity of CCl2 in CHB patients with cirrhosis and liver cancer, which promotes CHB progression and the development of liver cirrhosis and liver cancer." (PMID 39531472, 2024).
dementia (1 paper, 2022). Loss of intellectual abilities interfering with an individual's social and occupational functions. "Within the neurodegenerative group, two proteins (VKORC1 and STX1B) were shared between AD and PD, and two other proteins (QPCT and CD2AP) were shared between the clinical diagnosis of AD and AD based on both clinical diagnosis and family history of dementia." (PMID 35882878, 2022).
Hypertension (1 paper, 2024). The presence of chronic increased pressure in the systemic arterial system. "In this step, glutaminyl-peptide cyclotransferase (QPCT) was identified as a mediator of the protective effect of GNA1 against hypertension." (PMID 39596173, 2024). "Importantly, our work here showed that the QPCT-mediated glucosamine metabolism pathway is involved in the development of hypertension." (PMID 39596173, 2024). "Moreover, the beneficial role of the QPCT inhibitor in protecting against hypertension has been proven by multiple public databases." (PMID 39596173, 2024). "While these drugs have not yet been recognized as QPCT inhibitors for treating hypertension, further research on their potential beyond neurodegenerative diseases is warranted." (PMID 39596173, 2024).
islet cell tumors (1 paper, 2007). "Consistent with previously published findings, genes with significantly elevated expression in islet cell tumors included insulinoma-associated 1 (INSM1), glutaminyl-peptide cyclotransferase (QPCT), fibrinogen B beta polypeptide (FGB), peroxisomal biogenesis factor 7 (PEX7)." (PMID 17389914, 2007).
liver cancer (1 paper, 2024). An epithelial or non-epithelial malignant neoplasm that arises from the liver. "Although many studies have investigated the QPCT gene in tumors, relevant studies in liver cancer have not been reported." (PMID 39531472, 2024).
myeloma (1 paper, 2025). "Although glutaminyl-peptide cylotransferase (QPCT) and contactin 5 (CNTN5) are not currently known to have any clear function related to B-cell biology or myeloma development, both have been noted to be upregulated in the plasma cells of some patients with myeloma at the single-cell level." (PMID 40334107, 2025).
renal cell carcinoma (1 paper, 2022). "QPCT (glutaminyl-peptide cyclotransferase) is bound to HRAS and improves the stability of HRAS by inhibiting its ubiquitination degradation, which can activate the ERK signaling pathway and lead to sunitinib resistance in renal cell cancer." (PMID 36789694, 2022).
Sepsis (1 paper, 2025). Sepsis is defined as life-threatening organ dysfunction caused by a dysregulated host response to infection. "The prognosis of sepsis patients was strongly linked to S100A11, QPCT, and IFITM2 based on meta-analysis and survival analysis(P < 0.05).GSEA analysis showed that S100A11, QPCT, and IFITM2 were significantly enriched in ribosome-related pathways." (PMID 39854580, 2025). "Although this study provides preliminary evidence for S100A11, QPCT, and IFITM2 as potential biomarkers of sepsis, several limitations remain." (PMID 39854580, 2025). "In the sepsis group, the qPCR results showed that S100A11, QPCT, and IFITM2 expression levels were significantly higher in the sepsis group(P < 0.05)." (PMID 39854580, 2025).
cancer (6 papers, 2015 to 2025). A tumor composed of atypical neoplastic, often pleomorphic cells that invade other tissues. "QPCT is considered attractive therapeutic targets in many human disorders, such as neurodegenerative diseases, and a range of inflammatory conditions, as well as for cancer immunotherapy, because of their capacity to modulate cancer immune checkpoint proteins." (PMID 41306978, 2025).
tumor (5 papers, 2006 to 2025). "QPCT has been identified as a potential therapeutic target due to its role in modulating immune cell–mediated phagocytosis of tumor cells, and considerable efforts have been made to develop small-molecule inhibitors against this enzyme." (PMID 41306978, 2025). "Metadherin (MTDH), glutaminyl-peptide cyclotransferase (QPCT), topoisomerase II alpha (TOP2A), programmed death ligand 1 (PD-L1), and tumor-infiltrating lymphocytes (TILs) were evaluated in BC tissues pre-neoadjuvant for potential biomarkers." (PMID 35875123, 2022). "In accordance with our previous data, APOE, PMEL, QPCT, and SORT1 were specifically secreted in all metastatic tumor cell lines together with proteins involved in ECM deposition and adhesive proteins supporting the hypothesis of amyloid fibril deposition (Fig EV2F)." (PMID 32749065, 2020).
neurodegenerative disease (3 papers, 2021 to 2025). A disorder of the central nervous system characterized by gradual and progressive loss of neural tissue and neurologic function. "Over the past decades, reducing QPCT activity has mainly been applied to regulate pE-amyloid-β to prevent neurodegenerative diseases." (PMID 39596173, 2024). "In addition, differentially expressed genes in B cells were identified; both the upregulated genes (KIR3DL2, QPCT, PPP2R2B) and the downregulated genes (FRAT2, WWC3, SPG20) had certain connections with neurodegenerative diseases." (PMID 34880454, 2021). "In B cells, the upregulated genes KIR3DL2, QPCT, and PPP2R2B are all involved in neural function and neurodegenerative diseases, and the downregulated genes FRAT2 and WWC3 are involved in the Wnt/β-Catenin signaling pathway, which is associated with AD pathogenesis." (PMID 34880454, 2021).
infection (2 papers, 2024). The state of being infected such as from the introduction of a foreign agent such as serum, vaccine, antigenic substance or organism. "Of particular interest, the expression of 6 genes (VSIG4, LAMP1, QPCT, C1QB, TNFSF13, and JUN) can be used to distinguish the transcriptomic signature of a dormant infection from an uninfected joint replacement highlighting the potential for these markers in diagnosing a dormant infection." (PMID 39563367, 2024).
neurological diseases (1 paper, 2024). "MBD5, OGDHL, AUTS2, EGR3, QPCT, and ITGA8 are linked to neurological diseases." (PMID 39588153, 2024).
QPCT also shares sentences with these, for which no sentence is quoted: Alzheimer disease (14 papers); glomerulonephritis (2); adenocarcinoma (1); atherosclerosis (1); chronic kidney disease (1); diabetes (1); diabetic macular edema (1); leiomyoma (1); liver cirrhosis (1); osteoarthritis (1); pancreatitis (1); renal carcinoma (1); Senile plaques (1); septic shock (1); synucleinopathies (1).